PGRMC1 (progesterone receptor membrane component 1)
Diseases named in the same sentence as PGRMC1 in open-access papers (continued):
Sharing a sentence is not in itself a finding about the gene and the disease.
cancer (continued). "In addition to its role as a regulator of cancer cell survival, Pgrmc1 also affects cholesterol synthesis and steroidogenesis." (PMID 30356113, 2018). "However, some studies have also suggested that PGRMC1 is expressed on the surface of cancer and neuronal cells." (PMID 29445107, 2018). "PGRMC1 is a cytochrome-related protein with several implications in cancer." (PMID 27754849, 2016). "As such, PGRMC1 was one of the first proteins whose early cancer association was not at the level of expression, but at the level of differential phosphorylation." (PMID 27448967, 2016). "To further investigate the role of the dimerized form of PGRMC1 in cancer proliferation, we performed PGRMC1 knockdown-rescue experiments using FLAG-tagged wild-type and Y113F PGRMC1 expression vectors, in which silent mutations were introduced into the nucleotide sequence targeted by shRNA." (PMID 26988023, 2016). "In addition, we provide evidence linking PGRMC1 expression to cancer stem cells, which are notorious for their resistance to therapeutics, and the cancer stem cells in this study were highly resistant to powerful agents such as erlotinib and PD98059." (PMID 27867772, 2015). "The current study is, to our knowledge, the first report of PGRMC1 expression in cancer stem cells." (PMID 27867772, 2015). "Pgrmc1 (progesterone receptor membrane component 1) is a multifunctional 22 kDa protein with heme-binding and P450-activating capacity which was recognized under different names for roles in cell motility during neural development and in cancer, and apoptosis." (PMID 24027494, 2013). "Since PGRMC1 protects cancer cells from oxidative stress, it is tempting to speculate that 4A3COOHmethyl modulates the ability of PGRMC1 to function in this capacity." (PMID 19432992, 2009). "Determination of the thus far poorly defined role of PGRMC1 in cancer biology could prove to be of great relevance to clinical cancer therapists." (PMID 18922159, 2008). "However, PGRMC1 might be a promising target for novel therapeutic strategies using ferroptosis inducers in this type of cancer." (PMID 37887342, 2023). "Thus, PGRMC1 is a possible target for cancer therapy and inhibitors or antagonists of PGRMC1 may have potential therapeutic value." (PMID 34944026, 2021). "Therefore, we examined whether PGRMC1 engaged in cytosolic lipophagy formation in cancer cells with PGRMC1 expression when exposed to ferroptosis inducers." (PMID 34749765, 2021). "PGRMC1 Y180 was therefore evolutionarily acquired before the appearance of chordate organs, and the embryological differentiation processes that give rise to them, which immediately suggests how PGRMC1 may affect cancer cell plasticity." (PMID 32293262, 2020). "Moreover, PGRMC1-KD enhanced sensitivity to the anti-cancer drug, doxorubicin." (PMID 32867363, 2020). "Thus, HO-1 induction in cancer cells may inhibit the haem-mediated dimerization of PGRMC1 through the production of CO and thereby suppress tumour progression." (PMID 26988023, 2016). "Thus, PGRMC1 dimerization is important for cancer cell proliferation and chemoresistance." (PMID 26988023, 2016). "The expression of members of the progesterone receptor membrane component (PGRMC) family, particularly PGRMC1, is elevated in diverse types of cancers, particularly those of the female reproductive system." (PMID 40227710, 2025).
cancer (continued). "As such, dimerization was deemed necessary for the interaction of PGRMC1 with protein partners as shown for CYPs (1A2 and 3A4) and the epidermal growth factor receptor (EGFR), involved in signal transduction during cancer proliferation." (PMID 38804287, 2024). "Next, we performed expression profiling based on family cancer history and observed significant differential expression patterns for PAQR6, PGRMC1/2, and nPRs among HCC patients." (PMID 36980321, 2023). "The studies indicating that PGRMC1 and potentially PGRMC2 play important roles in the growth and development of these cancers and these issues are the focus of this review." (PMID 34885064, 2021). "In general, PGRMC1 is also known to interact with EGFR and further activates intracellular Akt signaling in cancer." (PMID 34970218, 2021). "While the roles of Pgrmc1 and the EGFR-mediated signaling pathway have been extensively studied in a variety of cancers, the role of Pgrmc1, its signaling pathway, and interaction with EGFR remain poorly understood in the context of HCC." (PMID 34069911, 2021). "The studies presented in the following paragraphs outline a potential role for PGRMC1 and PGRMC2 in regulating both metastasis and cancer stem cell function." (PMID 34885064, 2021). "GL and GlucoGL inhibit the interaction between PGRMC1 and EGFR, thereby suppressing EGFR-mediated signaling required for cancer progression." (PMID 34209885, 2021). "Progesterone receptor membrane component 1 (PGRMC1) and epidermal growth factor receptor (EGFR) are highly expressed in various cancers." (PMID 34069911, 2021). "Of note, PGRMC1 exists in protein complexes including EGFR and modulates its expression levels in multiple cancer cell lines (breast, lung, colon cancers) and affects their proliferation and chemoresistance." (PMID 34069911, 2021). "The heme-dimerized PGRMC1 interacts with the EGF receptor (EGFR) and cytochromes P450 to enhance cancer proliferation and chemoresistance, respectively." (PMID 34209885, 2021). "In agreement with this, GL, at approximately 50 μM, suppressed PGRMC1-mediated EGFR activation and LDL uptake, enhancing anti-cancer activity." (PMID 34209885, 2021). "To this aim, we used Western blot (WB) to study the expression levels of σ1, PGRMC1, and σ2/TMEM97 receptors in several human cancer cell lines, representing nine different cancer types." (PMID 33466391, 2021). "For the first time in the literature, the expression levels of σ1 receptor, PGRMC1, and σ2/TMEM97 were studied simultaneously by Western blot analysis in 23 human cancer cell lines." (PMID 33466391, 2021). "We hypothesized that the interaction of PGRMC1 with enzymes of the mevalonate pathway might alter their function and thus affects cholesterol synthesis, resulting in elevated cholesterol levels, which may provide energy and components supporting cancer metabolism." (PMID 32660617, 2020). "PGRMC1 binds to EGFR and cytochromes P450, and is known to be involved in cancer proliferation and in drug resistance." (PMID 26988023, 2016). "Haem-mediated PGRMC1 dimerization is required for interactions with EGFR and cytochromes P450, cancer proliferation and chemoresistance against anti-cancer drugs; these events are attenuated by either CO or haem deprivation in cancer cells." (PMID 26988023, 2016). "While xenograft tumor studies using human transformed cell lines in immunocompromised mice have suggested that PGRMC1 enhances tumor growth and chemoresistance, the exact role of members of the PGRMC family in cancer development in vivo remains unclear." (PMID 40227710, 2025). "Intriguingly, it was demonstrated that the nematode homologue of PGRMC1, VEM-1, physically interacts with C. elegans UNC-40, the nematode homologue of the mammalian cell surface receptor ‘deleted in colorectal cancer’ (DCC), which is one of the receptors mediating netrin-1 function." (PMID 39007013, 2024).
cancer (continued). "In terms of the relationship between autophagy and lipid peroxidation, progesterone receptor membrane component 1 (PGRMC1) suppresses SLC7A11 via autophagic degradation of lipids, known as lipophagy, and induces ferroptosis in paclitaxel‐tolerant persister cancer cells." (PMID 35342359, 2022). "Moreover, Diego A. Pedroza proved that PGRMC1 altered the PI3K/AKT/mTOR and EGFR signaling in TNBC cells, playing a crucial role in regulating the growth of cancer cells." (PMID 34746100, 2021). "Pgrmc1 is a non-canonical progesterone receptor related to the lethality of various types of cancer." (PMID 34069911, 2021). "However, σ1, PGRMC1, and σ2/TMEM97 were generally expressed differentially, even between cell lines of the same cancer type." (PMID 33466391, 2021). "Overall, we here provide novel data regarding expression—especially of PGRMC1 and σ2/TMEM97, for which very little is known —in different human cancer types and cell lines included in a significant tool for anticancer drug development, the NCI60 cell line panel." (PMID 33466391, 2021). "It is notable that PGRMC1 is able to activate intracellular Akt signaling in cancer through the epidermal growth factor receptor (EGFR) tyrosine kinase, the typical trafficking target for PGRMC1." (PMID 33767621, 2021). "Nevertheless, the Pgrmc1 KO mice showed a significantly lesser degree of lung metastasis, and we observed that the PGRMC1 protein is involved in FAK expression, EMT regulation, and cancer cell migration." (PMID 33832499, 2021). "Specific cancer characteristics such as, EMT, chemotherapy resistance, motility, anchorage-dependent growth, vascular endothelial growth factor (VEGF)-induction and metastasis are all influenced by PGRMC1." (PMID 32867363, 2020). "Although the over-expression of PGRMC1 reported in many different types of human cancers, systematic analysis of its oncogenic role of PGRMC1 has not been performed for any cancer." (PMID 31970154, 2019). "M0 (cancer has not spread to other parts of the body patients) samples were significantly enriched in groups with PGRMC1 low-expression groups (P < 0.0001)." (PMID 31970154, 2019). "Despite the functional role of PGRMC1 in aspects of tumor development, there is no sufficient evidence that PGRMC1 expression is clinical application enough significant for various cancers." (PMID 31970154, 2019). "Subsequent studies using cancer cells having a stable knockdown or overexpression of PGRMC1 challenged these conclusions since neither condition resulted in a change in binding of the σ2R radioligand, [3H]DTG17,18." (PMID 30443021, 2018). "It is known that high expression of BAX is associated with improved chemotherapy responsiveness whereas PGRMC1 has a negative impact on chemotherapy by promoting the survival of treated cancer cells." (PMID 24628760, 2014). "The S2R is of increasing interest in various research areas which do not consistently cross-reference Pgrmc1, including apoptosis, cancer metastasis, cocaine addiction, and ion channels." (PMID 24027494, 2013). "We demonstrate a higher abundance of hypophosphorylated PGRMC1 isoforms in the specific subpopulation of clinically relevant ER-α-negative cancers." (PMID 18922159, 2008). "Therefore, we examined whether PGRMC1 involved the connection between lipid droplets and mitochondria for increasing FAO in cancer cells." (PMID 34749765, 2021).
cancer (continued). "Compared to the non-cancerous ovary, PGRMC1 was present in greater abundance in clear cell carcinoma, endometroid carcinoma, and papillary serous cystadenocarcinomas with increasing staining intensity as these cancers progress from stage IIB to stage IIIC." (PMID 34885064, 2021). "In addition, PGRMC1 was shown to interact with FDFT1, SCD1 (SCD5 homologue) and is overexpressed in hormone receptor-positive breast cancer that correlated with enhanced cancer cell proliferation and lipid raft formation." (PMID 34440098, 2021). "Nevertheless, the roles of PGRMC1 in invasion and metastasis remain largely unknown, and there are no literature reports of the role of PGRMC1 in cancer invasion as we knew." (PMID 32672400, 2020). "Meanwhile, flow cytometric analysis found that an anti-PGRMC1 antibody recognizing the N-terminal domain (residues 1–46) of PGRMC1 was not able to bind to csPGRMC1 on cancer cells, although it was able to recognize intracellular PGRMC1 in saponin-treated cells." (PMID 30679694, 2019). "However, the possibility of multiple topologies of csPGRMC1 seems to be low because C3 recognizing the N-terminal domain of PGRMC1 was not able to recognize csPGRMC1 on hPSCs and some cancer cells." (PMID 30679694, 2019). "Progesterone-receptor membrane component 1 (PGRMC1/Sigma-2 receptor) is a haem-containing protein that interacts with epidermal growth factor receptor (EGFR) and cytochromes P450 to regulate cancer proliferation and chemoresistance; its structural basis remains unknown." (PMID 26988023, 2016). "PGRMC1 is detectable in amniotic-derived mesenchymal cells and has been identified as an important hormonal signaling intermediate in neuronal stem cells, but its expression and function in cancer-derived stem cells have not been determined." (PMID 27867772, 2015). "Our analysis suggests that PGRMC1 seems a novel oncogene for HNSC since its correlation with signature genes of tumor proliferation, metabolism and tumor metastasis, and its over-expression could be used as an indicator for clinical unfavorable prognosis of HNSC patients and many other cancer types." (PMID 31970154, 2019). "Recent studies have reported that GL and its derivatives can bind to PGRMC1 (progesterone receptor membrane component 1), inhibit the interaction between PGRMC1 and EGFR (Epidermal growth factor receptor), then inhibit HCT116 and HuH7 cancer cell proliferation, while GA does not bind to PGRMC1." (PMID 36313350, 2022). "Our data suggest that σ1, PGRMC1, and σ2/TMEM97 receptors are expressed in the majority of the 23 cell lines tested, exerting different expression patterns without showing any selectivity to a particular cancer type." (PMID 33466391, 2021). "Drug treatment with a PGRMC1 inhibitor, AG-205, triggered stem cell death whereas treatment with erlotinib and the ERK inhibitor, PD98059, did not, suggesting a specific role for PGRMC1 in cancer stem cell viability." (PMID 27867772, 2015).
tumor (56 papers, 2008 to 2025). "Conversely, a previous in vitro study showed that the knockdown of PGRMC1 in HCC cells promoted their proliferation while its overexpression caused the opposite effects, implying the tumor-suppressing role of Pgrmc1 in hepatocytes." (PMID 34069911, 2021). "Recently, independent studies showed a positive correlation between PGRMC1 expression levels and breast features associated with poor prognosis, further suggesting its role as tumor marker and strengthening PGRMC1 prognostic value for this malignancy." (PMID 34831222, 2021). "In tumor cells, agonists for sigma-2/PGRMC1 cause toxicity by triggering caspase 3 activation whereas sigma-2/PGRMC1 antagonists do not." (PMID 25390692, 2014). "Taken together, it can be rationalized that USMB can enhance the radiosensitization effect by activating or inactivating various membrane lipids or proteins including ceramide or PGRMC1, or by causing direct damage to DNA within tumour cells or by targeting tumour angiogenesis." (PMID 35457210, 2022). "However further experimental studies would be required in order to clarify the biological role of PGRMC1 in tumor stemness associated pathway, such as OCT3/SOX2/NANOG/KLF4." (PMID 34746100, 2021). "Tumor tissue-specific delivery of let-7i miRNA, which downregulates the expression of PGRMC1 and CYP19A1, reversed paclitaxel-induced chemoresistance." (PMID 38804287, 2024). "Expression of mRNA encoding PAQR7 and PAQR8 in a panel of OC cell lines was below the qPCR detection limit and was downregulated in tumour tissue samples, whereas high expression of PGRMC1 and PAQR4 mRNA was observed in rare subtypes of OC cell lines." (PMID 39464509, 2024). "PGRMC1 contributes to doxorubicin resistance by promoting tumor cell viability, proliferation, and epithelial-mesenchymal transition (EMT) induction." (PMID 38804287, 2024). "We evaluated expression of progesterone receptor (PR), progesterone receptor membrane component 1 (PGRMC1), relaxin-2, and transforming growth factor beta 1 (TGFβ1) in tumor tissue from 92 women with HGSC parous (n = 73) and nulliparous (n = 19)." (PMID 38578428, 2024). "The expression of PGRMC1 significantly correlated with the numbers of tumour-infiltrating neutrophils also in tissues from GBM patients." (PMID 37887342, 2023). "In the Hannover cohort, GBM patients with high tumour levels of PGRMC1 had a significantly poorer overall survival compared to patients with low levels of PGRMC1 (p = 0.010; log-rank)." (PMID 37887342, 2023). "Membrane-associated progesterone receptor component 1 (PGRMC1) inhibits SLC7A11 through autophagic degradation of lipids and induces ferroptosis in paclitaxel-resistant tumor cells." (PMID 36185243, 2022). "Upregulated PGRMC-1 protein expression and mRNA in malignant tissues, has been found to correlate with poor overall survival, poor quality of life, and decreased tumor-free interval related to increased metastases and tumor size." (PMID 34830233, 2021). "PGRMC1 knockdown is associated with increased chemosensitivity of human endometrial xenograft tumors to doxorubicin, paclitaxel and carboplatin, followed by a fourfold decrease in the tumor volume in comparison with PGRMC1-intact controls." (PMID 34683909, 2021). "PGRMC1 expression promoted tumor growth and decreased the chemosensitivity of human xenograft tumors to paclitaxel." (PMID 34749765, 2021). "In our previous studies, PGRMC1 expression was found to correlate with larger tumor size and lymph node metastasis in primary ER-negative breast cancer tissues." (PMID 34746100, 2021). "Animal experiments showed that the in vivo tumor growth was promoted by PGRMC1 expression and was more significantly inhibited in the PGRMC1-expressing tumors by the treatment of sulfasalazine, an xCT inhibitor." (PMID 34749765, 2021).